RBM10 (RNA binding motif protein 10)
Diseases named in the same sentence as RBM10 in open-access papers (continued):
Sharing a sentence is not in itself a finding about the gene and the disease.
pancreatic adenocarcinoma (2 papers, 2016 to 2025). "RNA-binding motif protein-10 (RBM10) plays a role in pancreatic adenocarcinoma (PAAD), though its precise underlying mechanism remains unclear." (PMID 40740233, 2025). "To understand the relationship between RBM10 and immune infiltration in pancreatic adenocarcinoma (PAAD), we analysed PAAD data from the TCGA database." (PMID 40740233, 2025).
acute myeloid leukemia (1 paper, 2025). Acute myeloid leukemia (AML) is a group of neoplasms arising from precursor cells committed to the myeloid cell-line differentiation. "Such mutations, including hotspots in SF3B1 and U2AF1 and loss-of-function events in FUBP1, RBM5, RBM10, and ZRSR2, are recurrent in myelodysplastic syndromes, acute myeloid leukemia, chronic myelomonocytic leukemia, and multiple solid tumors 8,42–45." (PMID 41279721, 2025).
bladder tumours (1 paper, 2025). "The number of bladder tumours with truncating mutations in RBM10 and CDKN1A is also significantly higher across men than women." (PMID 41062697, 2025). "In summary, clonal selection in normal bladder differs between men and women, mirrored by an increased number of mutations in RBM10 and CDKN1A in male bladder tumours." (PMID 41062697, 2025).
blood disease (1 paper, 2018). A disease that occurs in the blood. "The possibility that RBM11 modulates the splicing of CCND1, and an array of oncogenic genes in EWS, is consistent with known roles for related RNA binding proteins (RBM), including RBM10, RBM15 and RBM25, which alter gene splicing to promote various forms of blood disease and cancer." (PMID 30093970, 2018).
campomelic dysplasia (1 paper, 2026). "These genes are associated with recognizable syndromes such as (acampomelic) campomelic dysplasia (SOX9), cerebro‐costo‐mandibular syndrome (SNRPB), SATB2‐associated syndrome (Glass syndrome, SATB2), Catel‐Manzke syndrome (TGDS), TARP syndrome (RBM10), and Stickler syndrome (COL2A1, COL11A1)." (PMID 41077824, 2026).
cleft palate (1 paper, 2012). Cleft palate is a fissure type embryopathy that affects the soft and hard palate to varying degrees. "Finally, deep sequencing of exons on the X chromosome identified RBM10 as the gene causing TARP (MIM 311900), a syndromic form of cleft palate." (PMID 22723972, 2012).
cutaneous squamous cell carcinoma (1 paper, 2024).
dengue virus infections (1 paper, 2025). "Recent research has identified the antiviral role of RBM10 in dengue virus infection, which is mediated by the splicing of the antiviral protein spermidine/spermine acetyltransferase 1 (SAT1) and the activation of various pro-inflammatory cytokines." (PMID 40742131, 2025). "Notably, RBM10 has been shown to promote neuroinflammation during flavivirus infections while acting as a host restriction factor in dengue virus infections." (PMID 40742131, 2025).
developmental delay (1 paper, 2022). "Recently, a mild form of TARP with developmental delay and dysmorphic traits was reported in the patient having a missense mutation (NM_005676: c.965C>T, p.P322L) in the RRM2 RNA binding domain in RBM10." (PMID 36421828, 2022).
HIV-1 infection (1 paper, 2025). The type species of lentivirus and the etiologic agent of acquired immunodeficiency syndrome (AIDS). "Our findings identify RBM10 as a novel regulator in HIV-1 infection, affecting viral RNA transcription, and as a new target for Vpu in modulating viral replication." (PMID 40742131, 2025). "Our findings demonstrated that the overexpression of RBM10 inhibits virus production, while RBM10 knockdown has the opposite effect, as observed using the Env-pseudotyped virus and NL-4.3 virus, indicating that RBM10 can serve as a novel host restriction factor of HIV-1 infection." (PMID 40742131, 2025). "However, the role of RBM10 in the biogenesis of HIV-1 infection remains unexplored." (PMID 40742131, 2025).
in Sarcoma (1 paper, 2020). "In silico analysis and CLIP data revealed a number of well-characterized RBPs potentially binding to CREB, e.g., FUS/TLS (Fused in Sarcoma/Translated in Sarcoma) and RBM10 (RNA-binding protein motif 10)." (PMID 32347317, 2020).
metastatic melanoma (1 paper, 2017). A melanoma that has spread from its primary site to another anatomic site. "In addition, in patients with metastatic melanoma, high RBM10 expression was correlated with increased disease aggression." (PMID 28662214, 2017).
microcephaly (1 paper, 2017). A congenital or acquired developmental disorder in which the circumference of the head is smaller than normal for the person's age and sex. "This is supported by the finding that mutations in the splicing factor RNA-binding motif RBM10 cause abnormal mRNA splicing, microcephaly, PNH, and cerebellar hypoplasia." (PMID 28542170, 2017).
neuroblastoma (1 paper, 2025). Neuroblastoma (NB) is the most common solid, extracranial childhood tumor. "Immunohistochemistry indicated that when compared with ganglion cell neuroblastoma (GNB), lower immunostaining of RORB was concomitant with elevated RBM10 expression in NB tissues." (PMID 40899609, 2025).
renal cell carcinoma (1 paper, 2023). "In addition, we also found that RBM10 can upregulate the expression of E-cadherin, downregulate the expression of Vimentin, and inhibit the migration of renal cell carcinomas (RCC)." (PMID 37509501, 2023).
tumor (68 papers, 2015 to 2026). "Together, these findings uncover a previously unrecognized mechanism through which RBM10 exerts tumor-suppressive functions via circRNA regulation and highlight circHIPK3 as a promising biomarker and potential therapeutic target in RBM10-deficient LUAD." (PMID 41673707, 2026). "Downregulated RBM10 in malignant tissues, particularly in advanced-stage tumours, is linked with poorer prognosis for hepatocellular carcinoma patients." (PMID 40740233, 2025). "Due to limited case number, the association of RORB expression with tumor cell ploidy and prognostic values of RBM10/RORB axis in NB warrant further investigation via a larger series of cases with longer follow‐up duration." (PMID 40899609, 2025). "Combined, these data suggested that the loss-of-function mutation RBM10C761Y impaired the tumor suppressive role of wild-type RBM10 in CCA." (PMID 38576051, 2024). "RBM10 is recognized as a tumor suppressor whose mutations significantly alter mRNA isoform expression, thereby compromising its anti-tumor function." (PMID 38576051, 2024). "The results indicated that male patients with RBM10 inactivation aged over 65 years with G3 tumor stage were at higher risk." (PMID 37509501, 2023). "The results showed that the age of the patients in the high-risk group with RBM10 deletion, their gender, and their tumor stage and grade have certain risk correlations." (PMID 37509501, 2023). "In most tumors, RBM10 mutations are frequently occurred, which is closely related to tumor progression." (PMID 39282149, 2022). "Secondly, bioinformatics analysis was used to prove that RBM10 was highly associated with tumor immune cell infiltration." (PMID 39282149, 2022). "The effect of RBM10 deficiency on EGFR-mutant NSCLC established in this study sheds light on the role of tumor genetic heterogeneity in the multifaceted evolution of therapeutic resistance." (PMID 35579943, 2022). "Decreased PFS in the RBM10-mutant group was associated with a decreased initial tumor response (P = 0.0041)." (PMID 35579943, 2022). "Somatic mutations in RBM10 have also been detected in NSCLC tumours and were found to be associated with increased influx of CD8+ T cells and IFN‐G transcriptional signatures." (PMID 35231161, 2022). "We did not observe a significantly different association between the expression level of RBM10 mRNA and the stages of the tumor or with the molecular subtypes in other cancer types." (PMID 39282149, 2022). "Our findings provide insight by revealing a previously unappreciated role for co-occurring RBM10 deficiency in limiting the initial response to EGFR inhibitor treatment in human EGFR-mutant LA by suppressing tumor cell apoptosis." (PMID 35579943, 2022). "Here, we revealed that RBM10 deficiency had a significant positive association with anti-tumor immunity in LUAD, which implied a novel role of RBM10 in the progression of LUAD." (PMID 34367963, 2021). "In line with its mutational status in certain cancers, are studies that have demonstrated tumor suppressor‐associated roles for RBM10." (PMID 29274279, 2018). "Our findings revealed that RBM10 mutations likely affect its tumor suppressive activity, at least in large part, by interfering with its splicing regulatory functions." (PMID 28091594, 2017). "Furthermore, RBM10 is suggested to be a tumour suppressor, with single-gene somatic mutations linked to shorter progression-free survival in metastatic colorectal cancer patients." (PMID 40740233, 2025).
tumor (continued). "Moreover, RBM10 deficiency in cancer cells increased PD-1 expression in natural killer cells in vitro, reducing their tumour-killing ability." (PMID 40740233, 2025). "Notably, high RBM10 expression was associated with improved prognosis, suggesting a tumour‐suppressive role for RBM10." (PMID 40740233, 2025). "The C761Y mutation caused the loss of RBM10 tumor suppressor ability." (PMID 38576051, 2024). "RBM10 is an LUAD tumour suppressor, and its loss, due to mutations, could impact its interactions and lead to impaired RNA splicing." (PMID 37686122, 2023). "In the process of malignant tumor progression, the mutation frequency of RBM10 indirectly affects tumor proliferation and migration through different mechanistic pathways and plays an important role in the apoptosis process of malignant tumor cells." (PMID 37509501, 2023). "RBM10, one of the gene-unstable groups, is a significantly mutated gene in tumor cells." (PMID 37509501, 2023). "RBM10 mutations were associated with tumor stage, lymphatic metastasis, and 5-year survival." (PMID 36335386, 2022). "In general, these data strongly prove that RBM10 is highly associated with tumor immune infiltration and may inhibit or promote cancer progression by recruiting and regulating infiltrating immune cells." (PMID 39282149, 2022). "In addition, we further found that the RBM10 expression was closely related to tumor-associated macrophages (TAMs) in a variety of cancers through xCell." (PMID 39282149, 2022). "Moreover, our results also show that RBM10 is considerably linked with most of the immune checkpoint genes, tumor immune cell infiltration, tumor mutation burden, and microsatellite instability." (PMID 39282149, 2022). "RBM10 deficiency decreased EGFR inhibitor efficacy in patient-derived EGFR-mutant tumor models." (PMID 35579943, 2022). "In certain cases (e.g., case 1), RBM10 loss may mediate the escape from tumor cell apoptosis during initial treatment and before the subsequent emergence of acquired resistance mutations such as EGFR T790M that drive tumor cell proliferation." (PMID 35579943, 2022). "Our in vivo mouse model findings, coupled with these clinical observations, suggest that loss of RBM10 can limit the initial response to EGFR-targeted therapy by suppressing tumor cell apoptosis, leading to worse clinical outcomes for patients with EGFR-mutant LA." (PMID 35579943, 2022). "We hypothesize that the loss of tumor suppressor function of RBM10 could be crucial for tumorigenesis at the early stage of LUAD, but during the progression of LUAD, RBM10 deficiency activates anti-tumor immunity." (PMID 34367963, 2021). "In addition, CD8/CD3 ratio was higher in RBM10 mutant group (P=0.019), and CD4/CD3 ratio was lower (P=0.001), which further proved that the fraction of anti-tumor T cells are higher in patients with RBM10 mutations." (PMID 34367963, 2021). "Then, tumor clones containing RBM10 mutations may be swept by immune system, resulting in the replacement of RBM10 by other genes." (PMID 34367963, 2021). "Despite the divergent effects on tumor progression, these pathways are all related to immune response, and the results demonstrate that RBM10 deficiency might alter immunogenicity in patients with LUAD." (PMID 34367963, 2021). "Although most RBM10 mutations resulted in a decrease in its expression, in specific tumor types or developmental stages, these mutations also may lead to an increase in RBM10 expression and promote tumor growth." (PMID 33718153, 2021). "Mutations in exon 10 of RBM10 can significantly promote the proliferation and invasion of tumor cells, and the 5-year survival rate of patients with these mutations was significantly lower than that observed in healthy individuals (36.4 vs. 46.5% of RBM 10 wild type; χ2 = 5.466, P = 0.019)." (PMID 33718153, 2021).
tumor (continued). "Interestingly, as we observed in the RBM10 mutant tumours, cases harbouring mutations at codon 61 paradoxically exhibited histological and clinical features indicative of poor survival." (PMID 25855536, 2015). "In addition, a recent research confirms that the low RBM10 expression significantly increases the immune activity of LUAD and is negatively linked with CD8+ T cells having a tumor-suppressive effect, which makes it evident that RBM10 is linked with immune infiltration." (PMID 39282149, 2022). "In brief, we demonstrate that RBM10 deficiency could enhance anti-tumor immunity in LUAD." (PMID 34367963, 2021). "In brief, RBM10 deficiency could enhance anti-tumor immunity in LUAD." (PMID 34367963, 2021). "Furthermore, we hypothesize that the proportional differences between these two RBM10 variants can have two different effects on tumor promotion and inhibition." (PMID 33718153, 2021). "Additionally, RBM10 deficient population exhibited enhanced anti-tumor immunity." (PMID 34367963, 2021). "Both in vivo and in vitro models demonstrated that RBM10 knockdown enhances transmigration of tumor cells across the BBB and increases brain metastasis frequency in nude mice." (PMID 40069781, 2025). "An in vitro blood-brain barrier (BBB) model and brain metastasis-prone cell lines (BrM3) were established to confirm the brain metastatic potential of tumor cells following RBM10 knockdown." (PMID 40069781, 2025). "Quantification of differential splicing events between tumor clusters and normal tissues showed that clusters harboring mutations in U2AF1, RBM10, and CMTR2 had significantly more splicing alterations than WT tumors." (PMID 41198678, 2025). "Meanwhile, therapeutic potential and toxicity of RIP‐12 or melatonin in regulating RBM10/RORB axis deserve studies by using patient‐derived tumor xenografts or immune‐competent mice models." (PMID 40899609, 2025). "Conversely, RBM10 overexpression reduced the number of tumor cells crossing the BBB in the in vitro BBB model." (PMID 40069781, 2025). "Mechanistic studies have shown that SLFN11 stabilizes RBM10 and promotes NUMB exon 9 skipping by inhibiting TRIM21-mediated RBM10 degradation, a process that is critical for regulating anti-tumor immune responses." (PMID 40766331, 2025). "Meanwhile, RBM10 physically interacts with and represses RORB transactivation in liquid condensates, and possesses oncogenic properties in facilitating tumor growth and aggressiveness, indicating the crucial roles of RBM10/RORB/NF‐κB axis in NB progression." (PMID 40899609, 2025). "The optimal cutoff value for RBM10 expression was calculated in R software, and tumour samples were divided into RBM10 high and low expression groups." (PMID 40740233, 2025). "Pre‐clinically, treatment with inhibitory peptide blocking RBM10‐RORB interaction suppresses lysosomal biogenesis and aggressive features of tumor cells, highlighting the biological significance of RBM10/RORB/NF‐κB axis in NB progression." (PMID 40899609, 2025). "RBM10 wild-type protein is highly conserved among mammals and functions as a splicing regulator and a tumor suppressor in various cancers." (PMID 38576051, 2024). "RBM10 exerted a tumor suppressive effect in CCA and correlated with favorable prognosis of CCA patients." (PMID 38576051, 2024). "On the other hand, RBM10 has been identified as a tumor suppressor in various types of tumors, including OS, inhibiting proliferation and promoting apoptosis." (PMID 38735973, 2024). "Conversely, certain SFs, including QKI, RBM5, RBM6, and RBM10, act as tumor suppressors and exhibit anti-cancer characteristics." (PMID 39004679, 2024).